RNASE2 (ribonuclease A family member 2)
Description:
This is a non-secretory ribonuclease. It is a pyrimidine specific nuclease with a slight preference for U. Cytotoxin and helminthotoxin. Selectively chemotactic for dendritic cells. Possesses a wide variety of biological activities.
Synonyms: EDN; RNS2; RAF3
Tractability: Small molecule: a structure with a bound ligand is known; it has a binding pocket of medium quality. Antibody: its Gene Ontology location is reachable by antibodies, with high confidence; UniProt predicts a signal peptide or a membrane-spanning region. PROTAC: a small molecule that binds it is known.
Target class: Enzyme
Gene: Protein-coding gene on chromosome 14 (20,955,487 to 20,956,436, forward strand). Ensembl gene ENSG00000169385.
Subcellular location: Lysosome; Cytoplasmic granule
Pathways (Reactome):
Immune System: Neutrophil degranulation
Gene Ontology:
Molecular function: lipopolysaccharide binding; protein binding; RNA nuclease activity; nucleic acid binding; ribonuclease A activity
Biological process: chemotaxis; defense response to Gram-negative bacterium; defense response to Gram-positive bacterium; defense response to virus; induction of bacterial agglutination; innate immune response in mucosa; RNA catabolic process
Cellular component: extracellular exosome; azurophil granule lumen; extracellular region; lysosome
Genetic constraint (gnomAD): Loss-of-function variants: 0 observed, 0.0819 expected, observed/expected ratio (o/e) 0, 90% interval 0 to 1.89. That is too few expected variants to judge how well the gene tolerates losing a copy. Missense variants: 170 observed, 203.06 expected, observed/expected ratio (o/e) 0.84, 90% interval 0.74 to 0.95. Synonymous variants: 67 observed, 69.99 expected, observed/expected ratio (o/e) 0.96, 90% interval 0.79 to 1.17.
Homologues: Orthologues: chimpanzee RNASE2 (99% identical), rat Ear1 (50% identical), rat Ear1l1 (50% identical), rat Rnase2 (49% identical), mouse Ear6 (48% identical), mouse Ear10 (47% identical), mouse Rnase2b (47% identical), rat Rnase17 (47% identical), mouse Ear1 (47% identical), mouse Ear14 (47% identical), mouse Ear2 (47% identical), mouse Rnase2a (45% identical), and 1 more. Paralogues in human: RNASE3 (69% identical), RNASE6 (42% identical), RNASE8 (42% identical), RNASE7 (40% identical), RNASE1 (30% identical), RNASE4 (27% identical), ANG (22% identical), RNASE10 (19% identical), RNASE9 (19% identical), RNASE13 (18% identical), RNASE11 (14% identical), RNASE12 (12% identical).
Diseases named in the same sentence as RNASE2 in open-access papers:
RNASE2 is named in the same sentence as 87 diseases in open-access papers, as found by Europe PMC text mining. Sharing a sentence is not in itself a finding about the gene and the disease. The quoted sentences say what the papers report.
asthma (27 papers, 2013 to 2026). "RNASE2 and catalase (CAT) are highly expressed in eosinophils and have been shown to be predictive biomarkers for atopy and asthma, respectively." (PMID 25643280, 2015). "RNASE2 and catalase (CAT) are highly expressed in eosinophils and are predictive biomarkers of atopy and asthma, respectively." (PMID 25643280, 2015). "In addition, Airway Inflammation in Asthma pathway (CXCL8 and RNASE2) was enhanced in the monocyte population." (PMID 37495649, 2023). "In accordance, we found the eosinophil marker genes RNASE2 (ribonuclease A family member 2), RNASE3, SIGLEC8 (sialic acid binding Ig-like lectin 8) and IL5RA as well as PRSS33 (serine protease 33) being exclusively expressed in eosinophils in the deconvolved asthma data." (PMID 33076907, 2020).
eosinophilia (7 papers, 2011 to 2025). "Also, the analyses of post-mortem RNA-sequencing with COVID-19-infected lungs versus normal controls show the significant expression and upregulation of genes related to eosinophilia, such as CLC (Galectin-10), RNASE2 (EDN), and CCL11 (eotaxin-1)." (PMID 40710346, 2025).
gastric cancer (6 papers, 2021 to 2023). A primary or metastatic malignant neoplasm involving the stomach. "Similarly, a bioinformatics analysis from the TCGA database also indicated that RNASE2 mRNA expression is associated with the prognosis of patients with gastric cancer." (PMID 35747836, 2022). "The upregulation of RNASE2 in gastric cancer was associated with poorer survival." (PMID 34249481, 2021).
systemic lupus erythematosus (5 papers, 2020 to 2023). An autoimmune multi-organ disease typically associated with vasculopathy and autoantibody production. "As an immune-related molecule, RNASE2 is a biomarker of various immune system diseases, including chronic myelogenous leukemia, systemic lupus erythematosus, rheumatoid arthritis, and multiple myeloma." (PMID 36635413, 2023). "Consistently, we also found that plasma level of IL-10 in lupus patients were higher than those in normal subjects and positively correlated with peripheral RNASE2 expression." (PMID 35265065, 2022). "Meanwhile, RNASE2, usually highly expressed in eosinophils from normal subjects, was also significantly elevated in lupus monocytes." (PMID 35265065, 2022). "RNASE2 mRNA is elevated in peripheral blood mononuclear cells from patients with systemic lupus erythematosus, and RNASE2 silencing suppresses the production of age-associated B cell subsets in vitro." (PMID 35747836, 2022). "Our next question is how RNase2 affected the function of lupus monocytes so as to promote ABCs expansion." (PMID 35265065, 2022). "Since IL-10 signaling pathway was up-regulated in overall monocytes at MC, we next analyzed the expressions of ribonuclease A family member 2 (RNASE2) which can induce IL-10 secretion from monocytes and thus augment the age-associated B cells expansion in systemic lupus erythematosus." (PMID 37620910, 2023). "High expression of RNASE2 in lupus monocytes might contribute to promote B cell differentiation and Ig production." (PMID 35265065, 2022). "In addition, we demonstrated that both RNASE2 and IL-10 in peripheral blood of lupus patients were mainly derived from monocytes." (PMID 35265065, 2022). "It remains to be elucidated how RNASE2 regulates IL-10 production in lupus monocytes." (PMID 35265065, 2022).
COVID-19 (4 papers, 2020 to 2023). A disease caused by infection with severe acute respiratory syndrome coronavirus 2. "By searching for DTGs associated with IRGs shared between COVID-19 and IS, we identified eight DEGs interacting with two known databases of drug targets: JAK2, ORM1, RNASE2, TNFSF13B, CYBB, EIF2AK2, CD79B and CAMP." (PMID 36969251, 2023). "Interestingly, our gene expression analysis of post-mortem COVID-19 patient lungs revealed that the eosinophil associated genes, CLC, RNASE2 (EDN), and CCL11 were some of the most upregulated genes in COVID-19 lung tissue." (PMID 33777047, 2021). "Given reports of eosinopenia in COVID-19 patients, we were surprised to find that multiple eosinophil-associated granule genes were significantly upregulated in COVID-19 patient lung tissue, for example CLC (Galectin-10) and RNASE2 (EDN)." (PMID 33777047, 2021).
Sepsis (4 papers, 2022 to 2025). Sepsis is defined as life-threatening organ dysfunction caused by a dysregulated host response to infection. "Beyond these confirmed genes, this study also discovered three potential diagnostic genes for IE (CD177, IRAK3, RNASE2) and one potential diagnostic gene for sepsis (RNASE2) for the first time." (PMID 38332910, 2023). "The relative expression levels of GNMT, SEMA4B, FURIN, and RNASE2 were significantly lower in the sepsis group than those in the control group." (PMID 40526611, 2025). "We successfully identified four key biomarkers correlated with IE and Sepsis, namely CD177, IRAK3, RNASE2, and S100A12." (PMID 38332910, 2023). "Expression of three biomarkers (IRAK3, RNASE2, S100A12) was visualized in both HC and sepsis samples." (PMID 38332910, 2023). "While literature links NONO, FCAR, BMP6, RNF4, and RNASE2 to sepsis or Systemic Inflammatory Response Syndrome (SIRS), their interactions and the roles of PLEKHO1, OGFOD3, and CKAP4 in sepsis are less documented." (PMID 40665987, 2025). "Additionally, by comparing the expression profiles between disease samples and control samples, it was found that the expression levels of CD177, RNASE2, IRAK3, and S100A12 were significantly elevated in both IE and sepsis samples." (PMID 38332910, 2023).
acute lymphoblastic leukemia (3 papers, 2020 to 2022). Leukemia with an acute onset, characterized by the presence of lymphoblasts in the bone marrow and the peripheral blood. "RNASE2 is overexpressed in some cancers, including acute lymphoblastic leukemia and colorectal cancer." (PMID 33229623, 2020). "Moreover, the expression of RNASE2 was significantly upregulated in childhood acute lymphoblastic leukaemia." (PMID 33602220, 2021).
rheumatoid arthritis (3 papers, 2016 to 2023). A chronic, systemic autoimmune disorder characterized by inflammation in the synovial membranes and articular surfaces. "Elevated peripheral blood RNASE2 mRNA expression was validated by real-time PCR in 60 SLE patients, compared with 20 patients with rheumatoid arthritis (RA), 20 patients with primary Sjögren’s syndrome (SS) or 37 HC." (PMID 35265065, 2022).
viral infections (3 papers, 2018 to 2022). "The present study corroborates previous reports on RNase2 involvement in host response to viral infections." (PMID 35347428, 2022). "RNase2 has a high antiviral activity but no antibacterial activity in vitro, and is regulated during viral infection." (PMID 31312205, 2019).
colorectal cancer (2 papers, 2020 to 2022). A primary or metastatic malignant neoplasm that affects the colon or rectum. "RNASE2 expression is also significantly higher in colorectal cancer stem cells (CD133+) than in CD133− colorectal cancer cells." (PMID 35747836, 2022). "An abnormal expression of RNASE2 has been reported in colorectal cancer stem cells and bladder cancer tissues; however, the function and mechanism of RNASE2 in cancer cells has not been studied." (PMID 35747836, 2022).
glioma (2 papers, 2022 to 2023). A benign or malignant brain and spinal cord tumor that arises from glial cells (astrocytes, oligodendrocytes, ependymal cells). "In conclusion, RNASE2 is a novel marker associated with the diagnosis and prognosis of patients with glioma, and it promotes the malignant progression of gliomas through the PI3K/Akt signaling pathway." (PMID 35747836, 2022). "In terms of cancer, RNASE2 promotes the malignant progression of glioma through the PI3K/Akt signaling pathway." (PMID 36635413, 2023). "We found that RNASE2 was positively expressed in all glioma tissues, and that the proportion of patients in the high expression group was 68.79%." (PMID 35747836, 2022). "Next, we analyzed the expression characteristics of RNASE2 using glioma samples and explored its function by overexpressing and knocking down its expression in glioma cell lines." (PMID 35747836, 2022). "In glioma microarrays, 31.21% (54/173) and 68.79% (119/173) patients showed low and high RNASE2 protein expression levels, respectively." (PMID 35747836, 2022). "RNASE2 was identified as a differentially expressed gene (DEG) in glioma tissues using bioinformatics analysis." (PMID 35747836, 2022). "In this study, we investigated the role of RNASE2 in glioma using clinical samples, cell lines, and animal experiments." (PMID 35747836, 2022). "RNASE2 had a higher expression rate in the glioma tissues of patients with advanced-stage disease than in those of patients with early disease." (PMID 35747836, 2022). "This glioma tissue microarray has complete pathological information and follow-up information on the prognosis of all enrolled patients, which are important data for explaining the role of RNASE2." (PMID 35747836, 2022). "In this study, we aimed to analyze the expression pattern and role of RNASE2 in glioma." (PMID 35747836, 2022). "Taken together, our findings reveal that RNASE2 levels are related to the clinicopathological features of patients with glioma and that RNASE2 may play an oncogenic role by activating PI3K/Akt signaling." (PMID 35747836, 2022). "Correlation between RNASE2 levels and clinicopathological features of patients with glioma." (PMID 35747836, 2022). "The RNASE2 protein was positively expressed in all the 173 (100%) glioma tissues." (PMID 35747836, 2022). "In addition, RNASE2 had a higher expression rate in glioma tissues collected from patients who had died or relapsed at the time of follow-up than in those collected from patients who survived or did not relapse at follow-up." (PMID 35747836, 2022). "The expression characteristics of RNASE2 obtained in this study suggest that RNASE2 may play an oncogenic role in glioma." (PMID 35747836, 2022). "Therefore, we analyzed RNASE2 protein levels using glioma tissue microarrays." (PMID 35747836, 2022). "Moreover, we hypothesized that RNASE2 might play its role in the tumorigenesis of glioma by activating PI3K/Akt signaling." (PMID 35747836, 2022). "Furthermore, LY294002 blocked the effects of RNASE2 on the cell function of glioma cells." (PMID 35747836, 2022). "Moreover, RNASE2 knockdown had a suppressive effect on cell growth and metastasis, indicating that inhibiting RNASE2 expression may be a strategy to suppress the genesis and development of glioma." (PMID 35747836, 2022). "Hence, RNASE2 may be a novel molecular target for the development of targeted therapies against glioma." (PMID 35747836, 2022). "Our results revealed that RNASE2 may be a potential molecular target for glioma drug development." (PMID 35747836, 2022).
alcoholic cirrhosis (1 paper, 2023). "Therefore, our findings suggest that RNASE2 mono, IRF1 mono, IL1R2 mono, and H1-4 mono could be the origin of macrophages and may transform into two distinct types of monocytes and macrophages during the progression of alcoholic cirrhosis." (PMID 36845083, 2023).
Ataxia (1 paper, 2012). Ataxia refers to impaired coordination of voluntary muscle movement. "RNASE2– RNase A family, 2 (liver, eosinophil-derived neurotoxin) is a distinct cationic protein of the eosinophil’s large specific granule known primarily for its ability to induce ataxia, paralysis, and central nervous system cellular degeneration." (PMID 23185530, 2012).
bladder cancer (1 paper, 2022). "Proteomic analysis of urine showed that RNASE2 levels are higher in the urine of patients with prostate cancer than in that of patients with bladder cancer or benign prostate hyperplasia." (PMID 35747836, 2022).
clear cell renal cell carcinoma (1 paper, 2021). "A recent study figured out that RNASE2 could be a valuable prognostic predictor in clear cell renal cell carcinoma." (PMID 33602220, 2021).
heart failure (1 paper, 2022). Inability of the heart to pump blood at an adequate rate to meet tissue metabolic requirements. "In accordance with adjusted p < 0.05 and |fold-change|>1.5, five RBPs (EIF1AY, RPS4Y1, DDX3Y, RNASE2, and CSDC2) were found in heart failure LV myocardium specimens in comparison to nonfailing controls." (PMID 36313471, 2022).
HIV-1 infection (1 paper, 2017). The type species of lentivirus and the etiologic agent of acquired immunodeficiency syndrome (AIDS). "The authors linked the downregulation of RNASE2, RNASE3 and RNASE6 to enhanced susceptibility of Th17 cells HIV-1 infection." (PMID 28241075, 2017).
multiple myeloma (1 paper, 2022). "Moreover, we found that YY1 mutation could affect the expression changes of certain genes in some cancers; for example, in multiple myeloma, YY1 mutation could affect the expressions of ERMN, DUSP8, PRG2, BMF, and RNASE2 genes." (PMID 35791393, 2022).
renal cell carcinoma (1 paper, 2021). "Studies have identified that combination analysis of RNASE2 with other genes has independent prognostic value in kidney renal clear cell carcinoma and renal cell carcinoma." (PMID 34249481, 2021).
staphylococcus aureus infection (1 paper, 2022). An infectious process in which the bacteria Staphylococcus aureus is present. "For example, Clostridium difficile and Staphylococcus aureus infection caused release of RNase2, while Bifidobacteria, Hemophilus, and Prevotella species infection did not." (PMID 35347428, 2022).
tumor (22 papers, 2009 to 2025). "RNASE2 expression is associated with the activation of M2 macrophages, which secrete immunosuppressive factors that dampen the antitumor immune response and further promote tumor growth and immune suppression." (PMID 37999824, 2023). "RNASE2 has been shown to regulate the production of cytokines (e.g., Interleukin-4 (IL-4) and Interleukin-10 (IL-10)), which can modulate the immune response and promote an immunosuppressive microenvironment, allowing tumor cells to escape immune surveillance." (PMID 37999824, 2023). "The tumor suppressor effect of RNASE2 in MM and its molecular mechanisms need further study." (PMID 34249481, 2021). "Among them, RNASE2 was significantly upregulated (p < 0.01), and the expression results of related mRNA showed a similar trend (p < 0.01), which suggests a potential role for these genes in the tumorigenic processes or the adaptation of the tumor environment in KIRC." (PMID 38549669, 2024). "While existing studies have underscored the influence of immune-related genes on the tumor microenvironment, facilitating the progression of HCC51,52, this study marks the inaugural mention of RNASE2 in the context of HCC." (PMID 38553531, 2024). "The mRNA levels of TEK, BMP1, AR, SLC11A1, SLC40A1, and F2RL1 were significantly downregulated in tumor cells compared with normal cells, and CX3CL1 and RNASE2 were upregulated in tumor cells." (PMID 35004689, 2021). "The results indicated that, as NOL12, PABPC1L, RNASE2, RPL22L1, and OASL expression increased, tumor grade, AJCC stage, T stage, and M stage in KIRC patients increased." (PMID 33229623, 2020). "Additionally, TNMplot database analysis revealed that tumor tissues had greater levels of FCGR3A and RNASE2 mRNA expression than healthy tissues." (PMID 39574475, 2024). "NOL12, PABPC1L, RNASE2, RPL22L1, OASL, and YBX3 expression were significantly positively correlated with tumor grade and AJCC stage, while RBM47 expression was negatively correlated with tumor grade and AJCC stage." (PMID 33229623, 2020). "The expression of RNASE2 and LARP6 was slightly elevated in tumor tissue, and ANG was not collected in the Human Protein Profiles." (PMID 33589575, 2021).
cancer (13 papers, 2009 to 2024). A tumor composed of atypical neoplastic, often pleomorphic cells that invade other tissues. "There is less data on INHBE and RNASE2 in malignancies, except for some bioinformatics studies reporting their predictive value in cancer prognosis, indicating that more in-depth studies on their biological functions are necessary in the future." (PMID 36812479, 2023). "Bioinformatics analysis showed that RNASE2, an RNA-binding protein, was identified as a novel immune prognostic marker in multiple kinds of cancers." (PMID 35627105, 2022). "Among them, the upregulation from the early-stage cancer to more advanced stages were the strongest for RNASE2, SERPINE1, and CETP." (PMID 33828156, 2021). "For the genes that are only selected by MVSPL, UBE21 is connected to other frequently altered genes and RNASE2 is targeted by three cancer drugs." (PMID 31534156, 2019). "Through a study of the HPA repository, it was possible to determine that cancerous pancreatic tissues had higher levels of FCGR3A protein expression than normal tissues executed, but there was not a significant distinction in RNASE2 protein expression between cancer and healthy tissues." (PMID 39574475, 2024). "At present, there are no reports on the function of RNASE2 in cancer." (PMID 35747836, 2022).